SNORA47 (small nucleolar RNA, H/ACA box 47)
Synonyms: HBI-115
Gene: Small nucleolar RNA gene on chromosome 5 (77,080,434 to 77,080,571, reverse strand). Ensembl gene ENSG00000238961.
Gene Ontology:
Biological process: RNA processing
Cellular component: nucleolus
Homologues: Orthologues: chimpanzee SNORA47 (100% identical), macaque SNORA47 (96% identical), pig SNORA47 (87% identical), dog SNORA47 (85% identical), guinea pig SNORA47 (81% identical), mouse Snora47 (80% identical), rat Snora47 (75% identical).
Diseases named in the same sentence as SNORA47 in open-access papers:
SNORA47 is named in the same sentence as 14 diseases in open-access papers, as found by Europe PMC text mining. Sharing a sentence is not in itself a finding about the gene and the disease. The quoted sentences say what the papers report.
ameloblastoma (3 papers, 2017 to 2021). The most common odontogenic tumor, arising from the epithelial component of the embryonic tooth and usually affecting the molar-ramus region of the mandible or maxilla. "Small nucleolar RNAs (snoRNAs) comprise a particular group of noncoding RNAs, which role in odontogenic tumors is still unknown, although the overexpression of SNORD116-25, SNORA11, SNORA21, SNORA47 was previously demonstrated in ameloblastomas." (PMID 33680332, 2021). "The result corroborates that SNORA65, SNORA21, SNORA47, SNORD116-25 and LINC340, which were validated here by RT and qPCR assays, belonged to the top most significantly expressed snoRNAs and lncRNAs in ameloblastoma." (PMID 27965463, 2017). "We have in this study reported significantly higher expression of a number of snoRNAs (SNORD116-25, SNORA11, SNORA21, SNORA47 and SNORA65) in ameloblastoma." (PMID 27965463, 2017). "Further validation in an independent cohort points out the long non-coding (lncRNAs) and small nucleolar RNA (snoRNAs): LINC340, SNORD116-25, SNORA11, SNORA21, SNORA47 and SNORA65 as a distinct ncRNA signature of ameloblastoma." (PMID 27965463, 2017).
breast carcinoma (3 papers, 2025). "We found higher SNORA47 expression was linked to poorer survival outcomes in patients with Luminal A breast cancer." (PMID 40264043, 2025). "In this study, high SNORA47 expression was linked to unfavorable survival outcomes among patients with Luminal A breast cancer in The Cancer Genome Atlas (TCGA)." (PMID 40264043, 2025). "In our study, bioinformatics analysis has demonstrated that the expression level of SNORA47 is associated with the prognosis of Luminal A breast cancer." (PMID 40264043, 2025). "These discoveries augment our comprehension of the molecular mechanisms driving breast cancer and suggest that SNORA47 could serve as a potential drug susceptibility marker." (PMID 40264043, 2025). "To examine the way SNORA47 influences the stemness phenotype and drug responsiveness of breast cancer cells, we transfected SNORA47 and anti-SNORA47 ASOs into MCF-7 and T47D cells and used qRT-PCR to verify changes in SNORA47 expression." (PMID 40264043, 2025). "Western blotting analysis revealed that the upregulation of Nanog, OCT4, and SOX2 was observed in breast cancer cells that exhibited overexpression of SNORA47, whereas a downregulation of these markers was evident in cells treated with ASOs targeting SNORA47." (PMID 40264043, 2025). "Meanwhile, another Team Ang Zheng found that SNORA47 affected stemness and chemotherapy sensitivity of Luminal breast cancer cells via EBF3/RPL11/c-Myc axis, providing a new direction for precision therapy of Luminal breast cancer patients." (PMID 40567603, 2025). "In contrast to the vector control group, the effective knockdown of EBF3 markedly suppressed the upregulated expression of Nanog, OCT4 and SOX2 in MCF-7 and T47D breast cancer cells that exhibited overexpression of SNORA47." (PMID 40264043, 2025). "To investigate how SNORA47 affects breast cancer cell stemness and drug sensitivity, we used RNA pull down experiments and searched for proteins that interact with SNORA47 by means of LC-MS." (PMID 40264043, 2025). "Via qRT-PCR analysis, our results indicated that SNORA47 was highly expressed in fresh breast cancer tissues (P < 0.001)." (PMID 40264043, 2025). "SNORA47 is not only overexpressed in this breast cancer subtype but actively contributes to two critical cancer characteristics: the maintenance of tumor stemness and chemotherapy resistance." (PMID 41375049, 2025). "A recent discovery of particular clinical relevance is the role of SNORA47 in Luminal A breast cancer." (PMID 41375049, 2025). "Therefore, SNORA47 affected the stemness phenotype of breast cancer cells by influencing the interactions between EBF3 and RPL11, which consequently influenced the stemness phenotype and sensitivity of the breast cancer cells." (PMID 40264043, 2025). "To explore the expression of SNORA47, we examined the breast cancer dataset from TCGA." (PMID 40264043, 2025). "In the following, we investigated whether SNORA47 affects breast cancer cell stemness and drug sensitivity by regulating c-Myc expression." (PMID 40264043, 2025). "Likewise, the recent discovery of the SNORA47/EBF3/RPL11/c-Myc axis in breast cancer illustrates how snoRNAs can connect different levels of cellular regulation." (PMID 41375049, 2025). "The purpose of this research is to elucidate the intricate molecular interactions among SNORA47, EBF3, and RPL11 in breast cancer cells." (PMID 40264043, 2025). "Nevertheless, there has been no reported literature on the role of SNORA47 in relation to breast carcinoma." (PMID 40264043, 2025). "SNORA47, a member of the small nucleolar RNAs, has not been documented in the context of breast cancer, although it has been reported in lung cancer." (PMID 40264043, 2025). "To this end, we suspected that SNORA47 may affect the nucleolus-nucleplasm translocation of RPL11, which in turn promotes c-Myc expression to influence stemness and drug sensitivity of breast cancer cells." (PMID 40264043, 2025).
lung carcinoma (3 papers, 2017 to 2025). "SNORA65 overexpression in metastasised oral squamous cell carcinoma (OSCC), SNORA21 and SNORA47 in lung cancer were also reported previously." (PMID 27965463, 2017). "SNORA47 was reported to affect lung cancer progression through the regulation of EMT and apoptosis." (PMID 40264043, 2025). "Interestingly, SNORA65 has been correlated with metastasization in OSCC, SNORA21 and SNORA47 with lung cancer." (PMID 27965463, 2017). "Meanwhile, HBI-115, SNORA47, and ACA31 all have unique expression patterns in lung cancer, especially in LUSC, according to a study on the early stage of lung cancer; thus, this result validates the unique indicating effects of these snoRNAs on cancer subtyping even at an early stage." (PMID 31052553, 2019).
non-small cell lung carcinoma (2 papers, 2017 to 2021). A group of at least three distinct histological types of lung cancer, including non-small cell squamous cell carcinoma, adenocarcinoma, and large cell carcinoma. "The high expression of SNORA21 and SNORA47 in patients diagnosed with non-small cell lung cancer has been associated with poor overall survival." (PMID 33680332, 2021). "Higher expression of SNORA21 and SNORA47 has earlier been associated to poor overall survival in patients with non-small cell lung cancer." (PMID 27965463, 2017).
alcohol steatohepatitis (1 paper, 2024). "According to these studies, we selected four snoRNAs (snoRA12, snoRA47, snoRA80E, and snoRD126) for exploration in the context of non-viral-related causes, including non-alcoholic steatohepatitis (NASH), non-alcoholic fatty liver diseases (NAFLD), and alcohol steatohepatitis." (PMID 39022679, 2024).
hepatocellular carcinoma (1 paper, 2024). A malignant tumor that arises from hepatocytes. "SNORA47 has been reported to be up-regulated in human hepatocellular carcinoma and associated with intrahepatic metastasis and lymphatic invasion." (PMID 38612790, 2024).
tumor (6 papers, 2017 to 2025). "SnoRA12, snoRA47, snoRA80E, and snoRD126 were studied by quantitative real-time PCR (qRT-PCR) in tumor and non-tumor adjacent tissue (NTAT) samples." (PMID 39022679, 2024). "In tumor tissues, snoRA12, snoRA47 and snoRA80E were upregulated, while snoRD-126 was downregulated compared to NTAT." (PMID 39022679, 2024). "Indeed, in tumours compared with non-tumour tissues, it has been found a down-regulation of SNORD113–1 associated with worse survival, and an up-regulation of SNORA47, SNORD126, SNORD78 and SNORD76 linked to the aggressive phenotype and poor prognosis of HCC." (PMID 35331312, 2022). "In summary, knockdown of SNORA47 significantly inhibited the tumor growth of NSCLC in vivo." (PMID 33816250, 2021). "However, when treated with PTX, SNORA47 did not exhibit significant proliferative capacity, suggesting that SNORA47-mediated tumor enlargement may be related to drug sensitivity." (PMID 40264043, 2025). "Finally, silencing of SNORA47 significantly inhibited the tumor growth of NSCLC in vivo." (PMID 33816250, 2021). "In a study involving 60 pairs of HCC tumor and NTAT, snoRA47 exhibited higher expression levels in tumors." (PMID 39022679, 2024). "It was found that the accumulated ncRNA levels (LINC340, LINC342, SNORD116-25, SNORA11, SNORA21, SNORA47, SNORA65; r = 0.5789, p-value = 0.0075) had a positive but moderate correlation with tumour size." (PMID 27965463, 2017).
cancer (3 papers, 2019 to 2025). A tumor composed of atypical neoplastic, often pleomorphic cells that invade other tissues. "Our analytical investigation demonstrated that the transcript levels of SNORA47 were markedly augmented in cancer samples (n = 1109) in contrast to normal tissues (n = 103) (P < 0.0001)." (PMID 40264043, 2025).
SNORA47 also shares sentences with these, for which no sentence is quoted: Luminal A (1 paper); nasopharyngeal carcinoma (1); non-alcoholic fatty liver diseases (1); non-alcoholic steatohepatitis (1); odontogenic tumors (1); oral squamous cell carcinoma (1).